CMTR2 (cap methyltransferase 2)
Description:
S-adenosyl-L-methionine-dependent methyltransferase that mediates mRNA cap2 2'-O-ribose methylation to the 5'-cap structure of mRNAs. Methylates the ribose of the second nucleotide of a m(7)GpppG-capped mRNA and small nuclear RNA (snRNA) (cap0) to produce m(7)GpppRmpNm (cap2). Recognizes a guanosine cap on RNA independently of its N(7) methylation status. Display cap2 methylation on both cap0 and cap1. Displays a preference for cap1 RNAs.
Synonyms: HMTr2; MTr2; AFT; FTSJD1; FLJ11171
Tractability: PROTAC: ubiquitination databases record sites on it.
Gene: Protein-coding gene on chromosome 16 (71,281,389 to 71,289,715, reverse strand). Ensembl gene ENSG00000180917.
Subcellular location: Nucleus; Cytoplasm
Subcellular location (Human Protein Atlas): Cell Junctions; Nuclear speckles
Gene Ontology:
Molecular function: methyltransferase cap2 activity; methyltransferase cap1 activity; methyltransferase activity; O-methyltransferase activity; RNA methyltransferase activity
Biological process: 7-methylguanosine mRNA capping
Cellular component: cytoplasm; nucleus
Genetic constraint (gnomAD): Loss-of-function variants: 42 observed, 53.84 expected, observed/expected ratio (o/e) 0.78, 90% interval 0.61 to 1.01. The upper end of that interval is the gene's LOEUF score, 1.01, which puts it in group 4 of 6, group 1 being the genes least tolerant of losing a copy. Missense variants: 907 observed, 945.02 expected, observed/expected ratio (o/e) 0.96, 90% interval 0.91 to 1.01. Synonymous variants: 326 observed, 334.53 expected, observed/expected ratio (o/e) 0.97, 90% interval 0.89 to 1.07.
Homologues: Orthologues: macaque CMTR2 (98% identical), dog CMTR2 (90% identical), pig CMTR2 (88% identical), rabbit CMTR2 (85% identical), rat Cmtr2 (80% identical), guinea pig CMTR2 (80% identical), mouse Cmtr2 (79% identical), tropical clawed frog cmtr2 (51% identical), zebrafish cmtr2 (42% identical), Drosophila melanogaster aft (27% identical), Caenorhabditis elegans cmtr-2 (17% identical). Paralogues in human: CMTR1 (16% identical).
Diseases named in the same sentence as CMTR2 in open-access papers:
CMTR2 is named in the same sentence as 8 diseases in open-access papers, as found by Europe PMC text mining. Sharing a sentence is not in itself a finding about the gene and the disease. The quoted sentences say what the papers report.
breast carcinoma (1 paper, 2025). "Exon inclusion in SPPL2A and exon exclusion in SMARCA1 were observed not only in LADC, but also in MDA-MB-231 cells, a breast cancer cell line with a truncating CMTR2 mutation." (PMID 41198678, 2025).
Lewis lung carcinoma (1 paper, 2025). "Additionally, CMTR2-knockout cells were generated from the mouse Lewis lung carcinoma (LLC) cell line." (PMID 41198678, 2025).
lung adenocarcinoma (1 paper, 2025). A carcinoma that arises from the lung and is characterized by the presence of malignant glandular epithelial cells. "Here, the authors map splicing patterns in lung adenocarcinoma, uncover a CMTR2-mutant subtype, and show its vulnerability to splicing modulators and immunotherapy." (PMID 41198678, 2025).
lung carcinoma (1 paper, 2025). "These splicing changes were validated by performing RT-PCR analysis of both CMTR2-knockout cell lines and the NCI-H1373 and NCI-H1915 lung cancer cell lines, which harbor truncating CMTR2 mutations." (PMID 41198678, 2025). "For instance, loss of CMTR2 promotes proliferation of KRAS-driven lung cancer cells." (PMID 41198678, 2025). "Additionally, the TRACERx study, a comprehensive multi-sampling analysis of lung cancer, identified CMTR2 as a target of truncal mutations." (PMID 41198678, 2025). "Next, we investigated whether CMTR2 deficiency is associated with potential therapeutic vulnerabilities in lung cancer." (PMID 41198678, 2025). "AT1965, an inhibitor of CMTR2 that is currently in clinical trials (NCT06234098), activates B cell-mediated immune responses in a lung cancer model and shows synergistic antitumor effects when combined with PD-1 inhibition." (PMID 41198678, 2025).
cancer (2 papers, 2025). A tumor composed of atypical neoplastic, often pleomorphic cells that invade other tissues. "In cancers with relatively high CMTR2 mutation frequencies, the mutations were often associated with hypermutated subtypes characterized by POLE mutations or microsatellite instability-high (MSI-H)." (PMID 41198678, 2025). "Intrinsic and CRISPR-Cas9-engineered CMTR2 mutations disrupt alternative splicing and sensitize cancer cells to sulfonamide-based RNA splicing modulators and immune checkpoint blockade therapy." (PMID 41198678, 2025). "We demonstrated that CMTR2-deficient cancer cells exhibit vulnerabilities in the mRNA splicing machinery and are sensitive to RBM39 degraders, such as sulfonamides." (PMID 41198678, 2025). "Furthermore, our analysis of TCGA PanCancer Atlas data revealed that LADC is the cancer type with the highest frequency of truncating CMTR2 mutations, further supporting the notion that CMTR2 is a target of smoking-related mutagenesis in LADC." (PMID 41198678, 2025). "Further investigation of the mechanisms of action of sulfonamides could lead to the identification of additional therapeutic targets for CMTR2-deficient cancers." (PMID 41198678, 2025). "The proportion of truncating CMTR2 mutations, especially nonsense mutations, was significantly higher in LADC (2.5%) than in other cancer types." (PMID 41198678, 2025). "The role of CMTR2 mutations in RNA splicing in cancer has not been investigated to date." (PMID 41198678, 2025).
tumor (1 paper, 2025). "To investigate how CMTR2 deficiency contributes to tumor formation, we conducted differential gene expression and pathway enrichment analyses using clinical specimens and cell models." (PMID 41198678, 2025). "The novel splicing events generate tumor-specific RNA isoforms, which suggests that CMTR2 deficiency can result in the production of splicing-derived neoantigens." (PMID 41198678, 2025). "Taken together, these results demonstrate that missense mutations in CMTR2 have deleterious effects on the function of this enzyme, further supporting the hypothesis that CMTR2 acts as a tumor suppressor gene." (PMID 41198678, 2025). "Functional analyses using both tumor-intrinsic and CRISPR-Cas9-engineered CMTR2-mutant cells showed that CMTR2 deficiency induces global alterations in RNA splicing and increases vulnerability of the splicing machinery." (PMID 41198678, 2025). "Quantification of differential splicing events between tumor clusters and normal tissues showed that clusters harboring mutations in U2AF1, RBM10, and CMTR2 had significantly more splicing alterations than WT tumors." (PMID 41198678, 2025). "In summary, these findings provide insight into the role of CMTR2 mutations in LADC and confirm previous reports of CMTR2 as a putative tumor suppressor gene, adding the observation that CMTR2 mutations are mostly smoking-associated." (PMID 41198678, 2025). "Detailed investigation of these Cap2 alterations and their functional consequences could reveal how CMTR2 influences tumor progression and immune responses." (PMID 41198678, 2025).
CMTR2 also shares sentences with these, for which no sentence is quoted: cutaneous melanoma (1 paper); uterine corpus endometrial carcinoma (1).